LINC02609 (long independently transcribed non-coding RNA 2609)
Gene: Long non-coding RNA gene on chromosome 1 (90,769,086 to 90,851,701, reverse strand). Ensembl gene ENSG00000233593.
Diseases named in the same sentence as LINC02609 in open-access papers:
LINC02609 is named in the same sentence as 5 diseases in open-access papers, as found by Europe PMC text mining. Sharing a sentence is not in itself a finding about the gene and the disease. The quoted sentences say what the papers report.
renal carcinoma (3 papers, 2021 to 2025). A carcinoma arising from the epithelium of the renal parenchyma or the renal pelvis. "To further clarify the expression of LINC02609 and SNHG17, we examined their expression in different renal cell lines and found that LINC02609 and SNHG17 were indeed significantly elevated in renal cancer cell lines." (PMID 40491925, 2025). "To investigate the effect of LINC02609, LINC01320 and LICN01116 in ccRCC, we down-regulated the expression of LINC02609, LINC01320 and LICN01116 in renal cancer cell lines (786-O and A498)." (PMID 38263248, 2024). "The expression of DOCK8-AS1 was significantly decreased, while the expressions of SNHG17, RUSC1-AS1, LINC02609, and LUCAT1 were increased significantly in patients with renal cancer." (PMID 35118117, 2021). "Particularly, we found that the distribution of renal cancer patients with low-risk values was relatively concentrated, which could be well distinguished from renal cancer patients with high-risk values by using those 5 FR-DELs (DOCK8-AS1, SNHG17, RUSC1-AS1, LINC02609, and LUCAT1)." (PMID 35118117, 2021). "In the present study, we identified 5 FR-DELs (DOCK8-AS1, SNHG17, RUSC1-AS1, LINC02609, and LUCAT1) that could be used as biomarkers to predict the outcome of renal cancer." (PMID 35118117, 2021). "Finally, we identified 5 FR-DELs (DOCK8-AS1, SNHG17, RUSC1-AS1, LINC02609, and LUCAT1) correlated with the OS of renal cancer patients independently through a series of bioinformatics analyses." (PMID 35118117, 2021).
renal cell carcinoma (1 paper, 2025). "The candidate biomarker LINC02609 regulates the progression of renal cell carcinoma through the MAPK signaling pathway." (PMID 40491925, 2025).
tumor (3 papers, 2021 to 2024). "Similarly, LINC02609 has two subtypes, and the expression trends of both subtypes were consistently downregulated in tumor cells." (PMID 38773560, 2024). "Based on the experimental data, in ccRCC, the HIF-2α/LINC02609/APOL1 axis can regulate the expression of APOL1, thus interfering with lipid storage, promoting endoplasmic reticulum homeostasis and regulating tumor progression in ccRCC." (PMID 38263248, 2024).
cancer (2 papers, 2021). A tumor composed of atypical neoplastic, often pleomorphic cells that invade other tissues. "Previous studies have demonstrated that the expressions of SNHG17, RUSC1-AS1, LINC02609, and LUCAT1 were significantly increased in many cancers." (PMID 35118117, 2021). "Of note, LINC02577 and LINC02609 have not yet been reported in human cancers." (PMID 33869028, 2021).
LINC02609 also shares sentences with these, for which no sentence is quoted: clear-cell renal cell carcinoma (1 paper).